BDNF (brain derived neurotrophic factor)
Diseases named in the same sentence as BDNF in open-access papers (continued):
Sharing a sentence is not in itself a finding about the gene and the disease.
benign breast diseases (1 paper, 2022). "In patients with benign breast disease, BCO40587 expression was positively correlated with BDNF (r = 0.67, P = 0.0003), HOTAIR (r = 0.6, P = 0.0019), CCAT2 (r = 0.52, P = 0.009), and PVT1 (r = 0.42, P = 0.44) expressions." (PMID 36376369, 2022).
benign prostatic hyperplasia (1 paper, 2022). A non-cancerous nodular enlargement of the prostate gland. "Overexpression of BDNF has also been detected not only in prostate cancer tissues, but also in benign prostatic hyperplasia (BPH) tissues, indicating that BDNF mainly contributes to stimulating cell proliferation." (PMID 36661494, 2022).
bladder urothelial carcinoma (1 paper, 2021). "However, BDNF played a detrimental role in bladder urothelial carcinoma (PFS: HR = 1.06, 95%CI = 1.00–1.11, p < 0.001), colon adenocarcinoma (PFS: HR = 1.44, 95%CI = 1.22–1.69, p < 0.001), and PAAD (PFS: HR = 1.29, 95%CI = 1.07–1.55, p < 0.001)." (PMID 34777634, 2021).
brain glioblastoma (1 paper, 2020). A WHO grade IV malignant astrocytic tumor that arises from the brain, usually the cerebral hemispheres. "Finally, we will give evidence of how the involvement of BDNF in the pathogenesis of brain glioblastoma has emerged, thus opening new avenues for the treatment of this deadly cancer." (PMID 33096634, 2020).
brainstem infarction (1 paper, 2023). "Third, co-overexpression of BDNF and Dlx2 promoted the directional differentiation of the grafted NSCs into GABAergic neurons, the dominant subtype of neurons lost in brainstem infarction." (PMID 37365654, 2023).
bronchiolitis (1 paper, 2024). Inflammation of the bronchioles characterized by swelling of the bronchioles and mucus accumulation. "Low serum BDNF in infants with severe bronchiolitis could be associated with a higher utilization by lung cells or with an altered production by lung cells." (PMID 39403060, 2024). "However, further studies are necessary to confirm and extend the fact that BDNF in the serum could be considered a key biomarker of lung inflammation to unveil another risk factor for severe bronchiolitis." (PMID 39403060, 2024). "Serum BDNF, measured at hospital discharge, was significantly lower in severe bronchiolitis (expressed as O2-supplemented infants)." (PMID 39403060, 2024). "In the present pilot study, we aimed to disclose the presence of serum BDNF in infants hospitalized with bronchiolitis at discharge as a disease severity indicator." (PMID 39403060, 2024). "In conclusion, this study shows that infants affected by bronchiolitis needing O2 supplementation decreased BDNF serum levels at the time of discharge." (PMID 39403060, 2024). "We predicted that BDNF may help in the prediction of the clinical course of bronchiolitis." (PMID 39403060, 2024). "Also, the absence of controls needed for the comparison of BDNF levels in our sample may be considered a limitation in the understanding of the role of BDNF as a biomarker of the clinical course of bronchiolitis and as a prognostic index." (PMID 39403060, 2024). "However, speculations meant to explain the low BDNF in infants with severe bronchiolitis may be proposed." (PMID 39403060, 2024). "BDNF is constitutively expressed in smooth muscle cells and epithelium of the lower respiratory tract, and as it is released during inflammatory conditions, serum levels may have a relevant role in the prognosis of infants with bronchiolitis." (PMID 39403060, 2024).
bronchopulmonary dysplasia (1 paper, 2023). Bronchopulmonary dysplasia is a chronic respiratory disease that results from complications related to lung injury during the treatment of infant acute respiratory distress syndrome in low-birth-weight premature infants or from abnormal lung development in older infants. "Meanwhile, CDK5 promotes apoptosis of hippocampal neurons via modulating apoptosis‐related proteins, thereby downregulating BDNF is secondary to brain damage caused by bronchopulmonary dysplasia." (PMID 36964998, 2023).
bruxism (1 paper, 2021). Excessive clenching of the jaw and grinding of the teeth. "We aimed to study whether sequence variants in genes involved in stress regulation pathways: NTRK2 and BDNF, may be associated with awake bruxism susceptibility, clinical presentation, and patients’ perceived stress level." (PMID 34610834, 2021).
catalepsy (1 paper, 2024). A nervous system disorder characterized by diminished responsiveness and consciousness, and rigidity of the body. "The selective breeding to high predisposition to catalepsy is associated with depressive-like features and sensitivity to BDNF and fluoxetine (selective 5-HT reuptake inhibitor) treatment." (PMID 38473717, 2024).
Cerebellar atrophy (1 paper, 2025). Cerebellar atrophy is defined as a cerebellum with initially normal structures, in a posterior fossa with normal size, which displays enlarged fissures (interfolial spaces) in comparison to the foliae secondary to loss of tissue. "Frontal, parietal, caudate, and cerebellar atrophy have been documented in the presence of low CSF β-amyloid and BDNF." (PMID 40137505, 2025).
cerebellar degeneration (1 paper, 2025). Degeneration of the cerebellum. "Therefore, first of all, to assess those putative neurotrophic factors that may be useful against neuronal death in our model, we carried out gene and protein analyses of BDNF, IGF1, VEGF-A, and VEGF-B along the period of cerebellar degeneration of PCD mice." (PMID 39859255, 2025).
cerebral amyloid angiopathy (1 paper, 2015). "Here, we reported that the deletion of AQP4 exacerbated cognitive deficits of 12-moth old APP/PS1 mice, with increases in Aβ accumulation, cerebral amyloid angiopathy and loss of synaptic protein and brain-derived neurotrophic factor in the hippocampus and cortex." (PMID 26526066, 2015).
cerebral edema (1 paper, 2020). "Our data show that piperine treatment can reduce the degree of cerebral edema, down-regulate TNF-α, IL-1β, and BDNF, decrease the reactivity of GFAP in the hippocampus, and inhibit TBI-induced seizures." (PMID 32655468, 2020).
cerebral toxoplasmosis (1 paper, 2022). Infections of the brain caused by the protozoan toxoplasma gondii that primarily arise in individuals with immunologic deficiency syndromes (see also aids-related opportunistic infections). "Moreover, PACAP promoted neuronal health likely via BDNF/p75NTR axis modulation, resulting in diminished dysregulation of the neuronal network with implications on glutamatergic and GABAergic signaling inflicted by cerebral toxoplasmosis." (PMID 36403002, 2022).
cervical disease (1 paper, 2023). "BDNF is overexpressed in the preneoplastic cervical disease in HIV-positive women compared with HIV-negative controls." (PMID 37445902, 2023). "Logistic regression analysis showed that the HIV status is an independent predictor of BDNF expression in pre-invasive cervical disease when considered alone (crude OR 4.6, 95% CI 0.027–20.347; p = 0.046) and when analyzed with other co-factors (adjusted OR 6.786, 95% CI 1.084–42.476; p = 0.041)." (PMID 37445902, 2023). "This is the first study to evaluate the immunohistochemistry expression of BDNF and NGF in the preneoplastic cervical disease according to HIV infection, possibly highlighting the role of BDNF as a mediator of cervical dysplastic and neoplastic progression, enhanced by HIV infection." (PMID 37445902, 2023). "Our study demonstrated that BDNF expression in the preneoplastic cervical disease is higher in HIV-infected women compared with non-infected controls." (PMID 37445902, 2023). "In preneoplastic cervical disease, BDNF expression is higher in HIV-infected women than in non-infected controls, and this is independent of the clinical features of the patients and from the presence of the HPV-HR genotype." (PMID 37445902, 2023). "Therefore, we aimed to investigate whether BDNF and NGF are overexpressed in preneoplastic cervical disease from HIV-infected women." (PMID 37445902, 2023).
Chagas cardiomyopathy (1 paper, 2018). A disease of the cardiac muscle developed subsequent to the initial protozoan infection by trypanosoma cruzi. "Serum brain-derived neurotrophic factor (BDNF) levels have been shown to be lower in patients with Chagas cardiomyopathy (ChC) than in patients with non-dilated chagasic cardiomyopathy." (PMID 30133549, 2018).
Charcot arthropathy (1 paper, 2013). "Considering these findings, BDNF and NGF, also known to be bone anabolic factors, may be upregulated in Charcot arthropathy, leading to development of intra-articular giant ectopic ossification." (PMID 24151574, 2013).
cholangiocarcinoma (1 paper, 2026). A carcinoma that arises from the intrahepatic biliary tree (intrahepatic cholangiocarcinoma) or from the junction, or adjacent to the junction, of the right and left hepatic ducts (hilar cholangiocarcinoma). "Our previous study demonstrated that the acetylcholine (Ach)/CHRNA5 axis promotes PNI progression in cholangiocarcinoma by upregulating BDNF expression through activation of the CAMKII/GSK3β/β‐catenin signaling pathway." (PMID 41556039, 2026). "Moreover, we discovered that Ach signaling could stimulate BDNF expression, increasing nerve infiltration in cholangiocarcinoma." (PMID 41556039, 2026).
cholestasis (1 paper, 2025). Impairment of the bile flow caused by obstruction within the liver, or outside the liver in the bile duct system. "However, no significant positive correlations were observed between BDNF levels and markers of hepatocellular injury or cholestasis." (PMID 40806277, 2025).
chronic cholecystitis (1 paper, 2013). "Therefore, we found in the current study that positivity rates of were significantly higher for BDNF and significantly lower for BMPR1A in gallbladder adenocarcinoma compared with peritumoral adenomatous polyp, and chronic cholecystitis tissues." (PMID 23531103, 2013). "In addition, the BDNF positivity and BMPR1A negativity in peritumoral tissues, polyps, and chronic cholecystitis epithelium was accompanied by moderate or severe dysplasia." (PMID 23531103, 2013).
Chronic constipation (1 paper, 2019). Constipation for longer than three months with fewer than 3 bowel movements per week, straining, lumpy or hard stools, and a sensation of anorectal obstruction or incomplete defecation. "Administration of either human recombinant BDNF or a BDNF analog to both healthy human subjects and patients with chronic constipation accelerated colonic motility and increased stool frequency." (PMID 30794676, 2019).
Chronic Hepatitis C (1 paper, 2015). "Brain-derived neurotrophic factor in patients has been found to be related with Chronic Hepatitis C." (PMID 25707620, 2015).
chronic spontaneous urticaria (1 paper, 2022). "Moreover, a significantly increased level of BDNF in the serum and altered skin was noticed in patients with chronic spontaneous urticaria." (PMID 36362520, 2022).
ciliopathy (1 paper, 2014). A genetic disorder of the cellular cilia or the cilia anchoring structures, the basal bodies, or of ciliary function. "If perturbation of TrkB activation in vivo in animal models of ciliopathies is observed, consistent with our observations in cells, this would support BDNF signaling as a possible mechanism for traits associated with these diseases." (PMID 24867303, 2014). "This will require investigation of the production of specific neuronal populations in the absence of ciliopathy proteins and determining what associated deficits, if any, may be dependent on proper embryonic BDNF signaling through TrkB." (PMID 24867303, 2014). "Taken together, these findings implicate a ciliopathy gene, BBS4, in the regulation of BDNF signaling through TRKB and suggest its importance in localization of the receptor to the axoneme of primary cilia." (PMID 24867303, 2014).
colonic carcinoma (1 paper, 2011). "BDNF and its receptors TrkB and p75NTR transcripts were detected at the expected size in tissues from patients' colonic carcinoma, whatever TNM stage." (PMID 21966426, 2011).
colorectal adenocarcinoma (1 paper, 2019). The most common type of colorectal carcinoma. "S100A4, but not MYLK, BDNF, and PCOLCE2, exhibited higher expression in colorectal adenocarcinoma, but lower expression in normal colon tissues." (PMID 31581665, 2019).
colorectal tumors (1 paper, 2013). "BDNF expression was significantly increased with increasing differentiation of colorectal tumors (well differentiated tumors versus moderate/poorly differentiated, P=0.017) and also increased with increasing T-staging (T-stage 1 versus 2 and 3, P=0.037)." (PMID 24255678, 2013).
convulsion (1 paper, 2021). A rapid and repeated body muscle contract that results in an uncontrolled shaking of the body. "A recent study showed that hesperidin can promote the activation of the CREB-BDNF pathway and maintain physiological levels of BDNF to inhibit pentylenetetrazol-induced convulsions in zebrafish." (PMID 34899313, 2021).
Corneal disease (1 paper, 2020). "Corneal disease subsequent to neurologic lesions may occur due to loss of axonal transport of trophic factors (e.g., brain-derived neurotrophic factor), as well as reduced tear production due to disruption of the neuronal circuitry essential for lacrimation, i.e., neurotrophic keratitis." (PMID 33575276, 2020).
cortical atrophy (1 paper, 2017). "Investigating the association of REST with previously identified plasma protein markers of MCI conversion to AD and cortical atrophy, we found strong associations with BDNF, RANTES, PAI-1 and NSE." (PMID 28585932, 2017).
dental anxiety (1 paper, 2024). "The primary predictor variable was serum BDNF level and the second predictor variable was dental anxiety scores before and after operation in patients." (PMID 38907644, 2024). "The aim of this study was to determine the relationship between dental anxiety and BDNF serum level through impacted third molar surgery." (PMID 38907644, 2024). "In present study, the use of serum BDNF level in the determination of dental anxiety through third molar surgery was evaluated." (PMID 38907644, 2024). "The aim of the study was to determine the patient's pre-procedural dental anxiety through the serum BDNF level detected with Elisa kits during the initial examination." (PMID 38907644, 2024). "There are no studies in the literature investigating the relationship between dental anxiety and BDNF." (PMID 38907644, 2024). "Key words:BDNF, dental anxiety, dental extraction, ımpacted molar surgery." (PMID 38907644, 2024). "Also, there were many variables (such as age, stress, physical activity, energy and addictions) in the sample minimizing the variables in future studies will shed light on the relationship between BDNF and dental anxiety in the literature." (PMID 38907644, 2024). "The hypothesis of a correlation between dental anxiety scale scores and serum BDNF level was rejected." (PMID 38907644, 2024). "In the future, it would be clinically very comforTable to detect dental anxiety from BDNF saliva analysis but, many factors such as the area where the saliva sample was taken, salivary flow-rate and timing to sample collection, stress, and infection affect the results." (PMID 38907644, 2024). "The aim of this study was to determine the correlation between dental anxiety and BDNF serum levels before and/or after surgery and to describe whether BDNF can be used as a marker for the detection of dental anxiety through impacted third molar surgery." (PMID 38907644, 2024). "The investigators hypothesize that dental anxiety is correlated with BDNF serum levels." (PMID 38907644, 2024). "However, since dental anxiety scales, we recommend investigating the correlation of the VAS and MDAS scales with BDNF in future studies." (PMID 38907644, 2024).
diarrhea syndrome (1 paper, 2025). "It is indicated that the therapeutic effect of Tongxie Yaofang in treating diarrhea syndrome caused by Ganqichengpi has a certain relationship with the level of BDNF, but its specific mechanism of action awaits further study." (PMID 40995228, 2025).
dissection (1 paper, 2021). The separation and isolation of tissues for surgical purposes, or for the analysis or study of their structures. "At first, although it has been shown that E2F2, IGF1R, and BDNF can cause arterial-related diseases, there is no research to prove the relationship between aortic dissection and these target gene." (PMID 34620091, 2021).
Dysphagia (1 paper, 2019). "There is some evidence that it can improve the cerebral blood flow and serum levels of brain-derived neurotrophic factor (BDNF) and nerve growth factor (NGF) in dysphagia patients, but still there is a lack of widely agreed evidence of a biologically-plausible basis for its effect." (PMID 31817993, 2019).
dystonic disorder (1 paper, 2021). A movement disorder characterized by sustained or intermittent muscle contractions, resulting in abnormal movements and/or postures. "In the advanced stage, the correlation turned negative, i.e., a lower BDNF concentration was more often associated with dystonic disorders." (PMID 34768699, 2021). "Analyzing our results, it can be assumed that, in the advanced HD stage, an increased level of BDNF is associated with the intensification of oculomotor and dysarthria disorders, but not with dystonic disorders, which are characteristic of the late stages of the disease." (PMID 34768699, 2021).
enteropathy (1 paper, 2020). "This study was performed to evaluate the effect of administration of the probiotic L.GG on the BDNF system in the course of PTG-induced enteropathy." (PMID 32120967, 2020). "In conclusion, data from this study demonstrate that the induced enteropathy affects the expression of the BDNF system in the rat brain." (PMID 32120967, 2020).
esophageal squamous cell carcinoma (1 paper, 2018). Esophageal squamous cell carcinoma (ESCC) is a type of esophageal carcinoma (EC) that can affect any part of the esophagus, but is usually located in the upper or middle third. "Indeed, in lung cancer, head and neck cancer, and esophageal squamous cell carcinoma, BDNF/TrkB/PI3K-AKT seem to be activated and linked to invasiveness." (PMID 30190671, 2018).
eye movement disorders (1 paper, 2021). "A higher BDNF level was associated with a severity of eye movement disorders, both in the direction of eye pursuit and speed of horizontal saccades, as well as a severity of speech disorders." (PMID 34768699, 2021).
female infertility (1 paper, 2022). Diminished or absent ability of a female to achieve conception. "One of estrogen's effectors, brain-derived neurotrophic factor, can be utilized as a biomarker to measure female infertility." (PMID 35419445, 2022).
fibrosis (1 paper, 2025). the formation of excess fibrous connective tissue in an organ or tissue in a reparative or reactive process. "Compared to those in the control group, BDNF and c-Fos were found to be downregulated in the dentate gyrus (DG) of the hippocampus in the BLM-induced fibrosis mice." (PMID 40655156, 2025).
gall bladder carcinoma (1 paper, 2013). "In the current study, increased expression of BDNF and decreased expression of BMPR1A were associated with increased risk of metastasis, regional invasion, and mortality in gall bladder carcinoma." (PMID 23531103, 2013).
gallbladder adenocarcinoma (1 paper, 2013). A carcinoma that arises from glandular epithelial cells of the gall bladder. "In the current study, we found that increased expression of BDNF or decreased expression of BMPR1A were independent predictors of poor DSS rates in gallbladder adenocarcinoma." (PMID 23531103, 2013). "Similarly, multivariate Cox regression analysis showed increased expression of BDNF or decreased expression of BMPR1A are independent predictors of poor DSS rates in gallbladder adenocarcinoma." (PMID 23531103, 2013).